PDK1 (pyruvate dehydrogenase kinase 1)
Diseases named in the same sentence as PDK1 in open-access papers (continued):
Sharing a sentence is not in itself a finding about the gene and the disease.
cervical cancer (continued). "Our study illustrated that NEAT1 modulates aerobic glycolysis in cervical cancer by upregulating PDK1 and promoted the migration, invasion and EMT of cervical cancer cells through aerobic glycolysis." (PMID 38733179, 2024). "In cervical cancer, the lncRNA NEAT1 has been identified as a contributor to tumor progression by activating the WNT/β-Catenin/PDK1 signaling axis." (PMID 39519092, 2024). "Mechanistically, NEAT1 modulated WNT/β‐catenin/PDK1 axis to facilitate aerobic glycolysis, resulting in EMT and metastasis in cervical cancer." (PMID 38733179, 2024). "The expressions of PDK1, β‐catenin and downstream molecules of the WNT/β‐catenin signaling pathway in cervical cancer cells and tissues were detected by western blotting, RT‐qPCR, immunofluorescence and immunohistochemistry assays." (PMID 38733179, 2024). "Here, it is revealed that aberrant pyruvate dehydrogenase kinase 1 (PDK1) expression is closely related to aerobic glycolysis in SIL and poor survival in patients with cervical cancer." (PMID 39499767, 2024). "Analysis of UALCAN data showed that PDK1 and SGK3 were over-expressed in cervical cancer compared with normal cervix." (PMID 33311486, 2020).
head and neck squamous cell carcinoma (8 papers, 2012 to 2025). A squamous cell carcinoma that arises from any of the following anatomic sites: lip and oral cavity, nasal cavity, paranasal sinuses, pharynx, larynx, and salivary glands. "Further, the role of PDK1 and related isoforms in drug resistance and disease prognosis has been documented—Elevated expression of PDK1 was shown to be linked with malignant phenotype and poor prognosis in head and neck squamous cell carcinoma." (PMID 28505181, 2017). "miR-375 expression suppressed the oncogene AEG-1/MTDH in head and neck squamous cell carcinoma, and knockdown of miR-375 increased the phosphorylation of Akt in BMPACs and post MI heart by targeting PDK-1." (PMID 28186962, 2017). "Restoration of the pyruvate dehydrogenase complex activity through inhibition of pyruvate dehydrogenase kinase 1 (PDK1) in head and neck squamous cell carcinoma cell lines led to reduced HIF-1a expression and tumor growth." (PMID 28397687, 2017). "Lastly, in head and neck squamous cell carcinoma (HNSCC),medicarpinmodulated the PTEN/AKT signaling pathway by increasing PTEN and AKTexpression while reducing PDK1 expression." (PMID 41280807, 2025).
Hyperglycemia (8 papers, 2015 to 2023). An increased concentration of glucose in the blood. "The promising and available effect of PDK1 in hyperglycemia-induced neuronal apoptosis and memory loss will identify the PDK1-lactic acid axis as a therapeutic target for the treatment of diabetic neuropathy." (PMID 37935660, 2023). "PDK1-regulated glucose metabolism provides a valid and effective strategy to ameliorate hyperglycemia-induced oxidative stress." (PMID 37935660, 2023). "PDK1 activator reduced FoxO1 nuclear translocation, which serves as the basis for subsequent transcriptional regulation during hyperglycaemia." (PMID 33108705, 2020). "We further demonstrated that PDK1 was involved in the upstream signalling response to hyperglycaemia." (PMID 33108705, 2020). "Hyperglycemia triggered apoptosis of EGC in vitro with decreased expression of Pdk1 and p-Akt, but increased expression of micorRNA375." (PMID 30140011, 2018). "Therefore, in this study, we aimed to investigate the role and mechanism of PDK1 in hyperglycemia-induced abnormal metabolism and neuronal injury." (PMID 37935660, 2023). "Hyperglycaemia-induced upregulation of several glycolytic genes was reduced by S6K inhibition, including aldolase B, Pdk1 and 6-phosphofructo-2-kinase/fructose-2,6-biphosphatase 3 (Pfkfb3), a bifunctional enzyme that converts F6P to F2,6BP, a potent activator of phosphofructokinase." (PMID 36376280, 2022). "In addition, the increase in activity of PDK1 produced by chronic hyperglycaemia was reversed by S6K inhibition." (PMID 36376280, 2022). "Western blot showed a reduction of both Pdk1 and p-Akt in EGCs treated with hyperglycemia." (PMID 30140011, 2018). "Moreover, our RNAseq analyses of islets exposed to acute hyperglycemia ex vivo show that O304 mitigates the immediate gene expression adaptions of β-cells to glucotoxic conditions, including increased mTORC1 signalling and Pdk1 expression." (PMID 37626210, 2023). "Next, we found that hyperglycemia triggers apoptosis of EGC in vitro, attenuates their cell viability, represses Pdk1 and PI3K/Akt pathway, and increases expression of micorRNA375." (PMID 30140011, 2018).
leukemia (8 papers, 2014 to 2024). A malignant (clonal) hematologic disorder, involving hematopoietic stem cells and characterized by the presence of primitive or atypical myeloid or lymphoid cells in the bone marrow and the blood. "Within 5 weeks after intrascaffold injection, a lethal leukemia developed from these scaffolds, but treatment with the PDK1 inhibitor significantly reduced tumor growth in these mice." (PMID 35232995, 2022). "JAM3 is highly enriched in leukemia-initiating cells and play an important role in the maintenance of leukemia-initiating cell stemness through LRP5/PDK1/AKT/GSK3β/β-catenin/CCND1 signaling pathways." (PMID 32979257, 2020). "We previously showed that DCA, a small molecule that inhibits PDK1 (a key regulator of the Warburg effect), blocks aerobic glycolysis in leukemia cells." (PMID 26231043, 2015). "The Warburg effect occurs in leukemia with the help of enzymes such as pyruvate kinases M2 (PKM2), lactate dehydrogenase A (LDHA), pyruvate dehydrogenase kinase 1 (PDK1), and fibroblast growth factor receptor 1 (FGFR1)." (PMID 34659946, 2021). "The Warburg effect in leukemia has been attributed to specific enzymes such as PKM2, LDHA, and PDK1." (PMID 34659946, 2021). "In leukemia, PKM2, LDHA, PDK1, and FGFR1 play an important role in establishing the Warburg effect." (PMID 34659946, 2021).
Obesity (8 papers, 2014 to 2025). Accumulation of substantial excess body fat. "Unfortunately, despite conducting in vivo genetic loss-of-function studies on the two leading candidate genes, Pdk1 and Itga6, we were unable to unambiguously point to a single causal gene that mediates the obesity phenotype." (PMID 36717164, 2023). "Together, these studies, under the described experimental conditions, were unable to confirm that loss of Pdk1 mediates the effect of the Moo1 locus on obesity." (PMID 36717164, 2023). "We hypothesized that genetic variation in or near Pdk1 or Itga6 causing reduced Pdk1 and Itga6 expression would promote obesity and impaired glucose tolerance." (PMID 36717164, 2023). "Using congenic mice, we found that obesity was affected by a ∼316 kb region, with only two known genes, pyruvate dehydrogenase kinase 1 (Pdk1) and integrin α 6 (Itga6)." (PMID 36717164, 2023). "We observed a positive correlation between PPARγ and PDK1/2 expression in visceral adipose tissue obtained from individuals with various degrees of obesity." (PMID 34552205, 2021). "In human adipose tissue, the expression of PDK1/2 was positively correlated with that of the adipogenic marker PPARγ and inversely correlated with obesity." (PMID 34552205, 2021). "We conclude that PDK1 and 2 are novel regulators of adipogenesis that play critical roles in obesity." (PMID 34552205, 2021). "Thus, Pdk1 is both a positional and functional candidate gene, with a reduction in PDK1 activity expected to promote obesity." (PMID 36717164, 2023). "Accordingly, PDK1 inhibits FoxO1 to regulate macrophage infiltration, and the PDK1/FoxO1 pathway in macrophages is essential for regulating macrophage polarization and insulin sensitivity in obesity." (PMID 37153549, 2023). "As the expression of PDKs has been noted in the adipose tissue of humans, pharmacological inhibition of PDK1/2 might also play a critical role in the prevention and treatment of obesity in humans." (PMID 34552205, 2021). "In this cohort, a positive correlation between the PDK1/2 and PPARγ expression levels was noted, suggesting that like PPARγ expression, PDK1 and PDK2 expression might be implicated in the pathogenesis of human obesity." (PMID 34552205, 2021). "Obesity decreased PDK1 Ser241 phosphorylation in the hippocampi of Zucker fa/fa rats." (PMID 25257559, 2014). "Thus, there is a possibility that these sequence changes leading to a gain or loss of function or other ESTs in the Moo1V strain region may alter obesity, instead of reduced Pdk1 or reduced Itga6 expression." (PMID 36717164, 2023). "Increased expression of PDK1 and PDK2 by JUN and FOS enforces HIF1a stability to facilitate adipocyte differentiation and obesity." (PMID 34552205, 2021). "This process could explain the decrease in PDK1/2 expression and increase in PDK4 expression in the adipose tissue of individuals with severe obesity." (PMID 34552205, 2021). "Additionally, previous studies have reported that obesity from a HFD decreases the activity of the hippocampal insulin signaling pathway, including the activity of IRS-1, PI3K, p-PDK1, p-AKT, and p-GSK-3β." (PMID 31311133, 2019).
Sepsis (8 papers, 2019 to 2025). Sepsis is defined as life-threatening organ dysfunction caused by a dysregulated host response to infection. "During sepsis, immune cells upregulate the expression of pyruvate dehydrogenase kinase 1 (PDK1), a kinase that phosphorylates and inhibits PDH." (PMID 40362448, 2025). "During sepsis, the expression and activity of PDK1 in immune cells is heightened, contributing to the dysfunction of mitochondrial metabolism." (PMID 33616039, 2021). "Of particular interest, during the hyper-inflammatory anabolic phase of sepsis, an increase in the expression and activity of pyruvate dehydrogenase kinase 1 (PDK1) consistently occurs." (PMID 33616039, 2021). "Although PDK1 and mTORC1/2 can both regulate the cellular metabolism, their signal pathways in the innate immunity during the secondary stimulation of sepsis are different." (PMID 32774145, 2020). "In the present study, the metabolism signaling of PDK1 and mTOR probably determines the innate immunity in sepsis." (PMID 32774145, 2020). "Myeloid deletion of PDK1 significantly tuned down the LPS-induced shock in the late sepsis (7 days after CLP) (p = 0.0275)." (PMID 32774145, 2020). "Although PDK1 and mTORC1/2 can both regulate the cellular metabolism, the signaling in the innate immunity in the secondary stimulation of sepsis is different." (PMID 32774145, 2020). "PDK1/mTOR signaling has been confirmed to regulate the metabolism of tumor, T cell, B cell, and NK cells but has rarely been associated with the myeloid cell metabolism especially in CLP-induced sepsis." (PMID 32774145, 2020). "Then, we analyzed whether the deleted PDK1 on myeloid cells could regulate the early survival of CLP-induced sepsis." (PMID 32774145, 2020). "The different role of PDK1 in the early and late stages of sepsis might be due to the tolerance of the inflammation in the late stage." (PMID 32774145, 2020). "Therefore, we generated the mice of PDK1 and mTOR deletion specially on the myeloid system and analyzed the early shock and the late immunotolerance during sepsis." (PMID 32774145, 2020). "PDK1/mTOR signaling is an important regulator within the metabolic signaling; thus, we wonder if PDK1/mTOR could be one target during sepsis." (PMID 32774145, 2020). "Both PDK1 and mTORC1/2 could not only regulate the cellular metabolism but also play important roles on the myeloid cells in the secondary stimulation of sepsis." (PMID 32774145, 2020). "The PI3K/PDK1/Akt pathway may also regulate different metabolism signaling of myeloid cells in the early and late stages of sepsis." (PMID 32774145, 2020). "In the present study, we found that PDK1 knockout in myeloid cells of CLP mice could aggravate the early septic shock but relieved the secondary inflammation at the late stage of septic shock in CLP-induced sepsis." (PMID 32774145, 2020). "The PI3K/PDK1/Akt pathway has been indicated to regulate both positively and negatively the expression of NFkB-dependent gene, which might be the reason of the two type inflammation states in the different stages of sepsis." (PMID 32774145, 2020). "However, PDK1 deletion could decrease the level of TNFα in the late stage of sepsis as the opposite of the early stage." (PMID 32774145, 2020). "After normalising the grey values, the expressions of p-PI3K/PI3K, p-AKT/AKT, p-MTOR/MTOR, HIF-1α, and PDK1 were decreased in CLP and LPS-induced sepsis, and the Warburg effector pathway was inhibited." (PMID 37434129, 2023). "Gene expressions of enzymes of the pyruvate dehydrogenase complex (Pdha1, Pdhb) were unaffected or decreased throughout sepsis, whereas pyruvate dehydrogenase kinase 3 (Pdk3), but not 1 (Pdk1), was upregulated." (PMID 39821755, 2025). "Overall, the mTOR complex deletion could aggravate the LPS-induced shock at the late stage of sepsis in the CLP mice, which is completely different with the PDK1 knockout." (PMID 32774145, 2020).
Sepsis (continued). "Overall, PDK1 deletion in myeloid cells could significantly alleviate the CLP-induced shock and cytokines in the late stage of sepsis." (PMID 32774145, 2020). "IL-6 in mouse serum was 10~20 pg/ml at 24 h and 48 h in both stages of sepsis, but its level did not change in PDK1 deletion mice in the late stage." (PMID 32774145, 2020). "Blockade of HMGB1 or macrophage PTEN deletion activates PI3K/PDK1/Akt and β-catenin signaling, which in turn enhances macrophage TGF-β leading to increased Foxp3 Treg induction while inhibiting Th17 cell differentiation during sepsis-induced lung injury." (PMID 31402909, 2019). "Moreover, PDK1 deletion could decrease the levels of IL-1β and IFN-γ in the late stage of sepsis, as the opposite of early stage." (PMID 32774145, 2020). "Moreover, changes in the expression levels of pyruvate dehydrogenase kinase 1(PDK1), glucose transporter 1(GLUT1), LDHA, and pyruvate kinase M2 (PKM2) regulate macrophage glycolysis, the release of proinflammatory cytokines, and macrophage activation during sepsis." (PMID 35090526, 2022).
triple-negative breast carcinoma (8 papers, 2014 to 2025). An invasive breast carcinoma which is negative for expression of estrogen receptor (ER), progesterone receptor (PR), and human epidermal growth factor receptor 2 (HER2). "Conversely, PGR, PDK1, and PEA15 are associated with Luminal A. Interestingly, in triple-negative breast cancer and ovarian cell lines, increasing PEA15 levels was shown to have an antitumor effect." (PMID 25183703, 2014). "Recent studies have shown that CRY1 inhibits the growth of triple-negative breast cancer (TNBC) cells, which is associated with its inhibition of Pyruvate Dehydrogenase Kinase 1 (Pdk1) expression, Pyruvate Dehydrogenase (PDH) phosphorylation, and glucose depletion." (PMID 39139571, 2024). "Here, using triple-negative breast cancer (TNBC) cell models, we demonstrate that MAPK4 can also enhance PDK1 protein synthesis, thus phosphorylate/activate PDK1 substrates beyond AKT." (PMID 37531320, 2023). "Such examples include UCN-01, a nonselective PDK1 inhibitor, which has shown promise in combination therapy with irinotecan for treatment of metastatic triple-negative breast cancer." (PMID 38035024, 2023). "To check whether PI3K, PDK1, and AKT are expressed in triple negative breast cancer and whether this expression correlates with relapse-free patient survival, we analysed data from the METABRIC study." (PMID 36013226, 2022).
ovarian tumor (7 papers, 2008 to 2021). "Our results suggest that PPARβ may have a distinct role in normal and malignant ovarian physiology, whereas PDK1 may be associated with ovarian tumour progression and metastasis." (PMID 18349831, 2008). "In this study, treatment with conditioned medium from CAFs isolated from ovarian tumor led to upregulation of PDK1 expression." (PMID 32071289, 2020). "Taken together, these observations suggest a correlative link between PDK1, c-myc, PKCα and caveolin-1 in ovarian tumours and are consistent with those observed in mammary epithelial cell models." (PMID 18349831, 2008). "Normal ovaries, benign, borderline, grades 1, 2 and 3 ovarian tumours of serous, muciuous, endometrioid, clear cell and mixed subtypes were analysed by immunohistochemistry for PPARβ and PDK1 expression." (PMID 18349831, 2008). "Significantly different PDK1 staining was observed between the benign/borderline and malignant ovarian tumours (χ2=22.45, d.f.=5, P<0.001)." (PMID 18349831, 2008). "In view of the association of PPARβ and PDK1 with cancer, we have examined the expression of PPARβ and PDK1 in normal ovaries and different histological grades of ovarian tumours." (PMID 18349831, 2008). "There was a gradual increase in the expression of PDK1 with increasing grades of ovarian tumours, with the bulk of the high-grade tumours demonstrating high expression of cytoplasmic and membrane-bound PDK1." (PMID 18349831, 2008). "In this study, we report the differential expression of PPARβ and PDK1 in normal human ovaries and ovarian tumours of different histological grades and subtypes." (PMID 18349831, 2008). "In this study, we have examined the expression of PPARβ and PDK1 in normal ovaries, benign tumours and the histological grades of ovarian tumours." (PMID 18349831, 2008). "A similar trend of heightened expression of both ILK and PDK1 in high-grade ovarian tumours may suggest enhanced activation of upstream PI-3 kinase and/or PPARβ cascades required for tumour progression." (PMID 18349831, 2008). "However, overexpression of PDK1 was evident in borderline and low- to high-grade ovarian tumours and is consistent with its known role in tumorigenesis." (PMID 18349831, 2008). "Twenty-two grades 2 and 3 ovarian tumours were examined for PDK1 expression." (PMID 18349831, 2008). "On the other hand, normal ovaries and a bulk of benign ovarian tumours demonstrate no significant expression of PDK1, but enhanced cytoplasmic and membrane expression of PDK1 was observed in borderline and low- to high-grade ovarian tumours." (PMID 18349831, 2008).
autosomal dominant polycystic kidney disease (6 papers, 2016 to 2025). Autosomal dominant form of polycystic kidney disease. "Seventy percent of the PDK1 sequence, a gene involved in autosomal dominant polycystic kidney disease, is duplicated, at least three times, across the genome with more than 95% homology." (PMID 26864517, 2016). "Moreover, autosomal dominant polycystic kidney disease (ADPKD) may coexist with TSC as large deletions of TSC2 may also involve PDK1, whose mutations are responsible for ADPKD." (PMID 29378663, 2018).
clear cell renal cell carcinoma (6 papers, 2020 to 2024). "We analysed the expression, subcellular distribution and clinicopathological correlations of PDK1-4 by immunohistochemistry of tumor tissue microarray samples from a cohort of 96 clear cell renal cell carcinoma (ccRCC) patients." (PMID 37147361, 2023). "Previous research has indicated that FTO promotes PDK1 expression by preventing the YTHDF2‐induced degradation of PDK1 mRNA via an m6A‐dependent mechanism, thereby facilitating the proliferation and migration of clear cell renal cell carcinoma." (PMID 39625183, 2024).